BDNF (brain derived neurotrophic factor)
Diseases named in the same sentence as BDNF in open-access papers (continued):
Sharing a sentence is not in itself a finding about the gene and the disease.
chondrosarcoma (continued). "Furthermore, transfection of cells with p85 and Akt mutant also inhibited BDNF-induced migration and β5 integrin expression in chondrosarcoma cells." (PMID 23874483, 2013). "Treating chondrosarcoma cell lines with BDNF (30–100 ng/mL) dramatically increased cell migration." (PMID 23892595, 2013). "We therefore examined whether BDNF promoted integrin expression and cell motility in human chondrosarcoma cells." (PMID 23874483, 2013). "Further, BDNF administration increases miR-214 expression during embryonic stem cell differentiation into endothelial cells, and it is found to promote vascular endothelial growth factor-C-dependent lymph angiogenesis by suppressing miR-624-3p in human chondrosarcoma cells." (PMID 38786102, 2024). "Thus, BDNF may be a new molecular therapeutic target in chondrosarcoma lymphangiogenesis and metastasis." (PMID 28771226, 2017). "We hypothesized that BDNF would help direct the metastasis of chondrosarcoma cells." (PMID 23874483, 2013). "Therefore, we next determined whether the TrkB receptor is involved in BDNF-mediated cell migration in human chondrosarcoma cells." (PMID 23874483, 2013). "Therefore, we hypothesized that any of these MMPs might be involved in BDNF-directed chondrosarcoma migration and invasion activity." (PMID 23892595, 2013). "Therefore, we hypothesized that ASK1 might be involved in BDNF-directed cell migration and invasion activity in chondrosarcoma." (PMID 23892595, 2013). "Because BDNF–TrkB promotes VEGF via PLCγ/PKCα and HIF−1α in human chondrosarcoma, VEGF, HIF−1α, and microvessel density are rational proxies for TrkB−axis output relevant to osteosarcoma vasculature and immune trafficking." (PMID 41383615, 2025). "Knockdown of BDNF leads to decreased VEGF expression and abolishes angiogenesis in in vitro studies and animal models of chondrosarcoma." (PMID 38375479, 2024). "In BDNF‐enhanced migration of chondrosarcoma, integrin β5 expression was up‐regulated through TrkB/AKT signalling cascade, while in BDNF‐mediated migration of microvascular endothelial cells, the up‐expression of integrin β3 was made via TrkB/ERK1/2 pathway." (PMID 32803867, 2020). "To verify the role of BDNF in VEGF-C-dependent lymphangiogenesis, we directly applied BDNF to chondrosarcoma cells, and determined VEGF-C expression and secretion." (PMID 28771226, 2017). "In this study, we investigated the role of BDNF in VEGF-C-dependent lymphangiogenesis, to elucidate its mechanism of action in human chondrosarcoma cells." (PMID 28771226, 2017). "Therefore, targeting BDNF may bea novel therapeutic strategy for the treatment of chondrosarcoma." (PMID 28771226, 2017). "This pattern is similar to the clinical expression of higher BDNF and VEGF-C expression versus lower miR-624-3p expression in human chondrosarcoma tissue compared with normal cartilage." (PMID 28771226, 2017). "Knowing more about the mechanism of BDNF in VEGF-C expression and lymphangiogenesis in human chondrosarcoma would improve our understanding as how to prevent chondrosarcoma angiogenesis and metastasis, which currently lacks effective adjuvant treatment." (PMID 28771226, 2017). "Brain-derived neurotrophic factor increases VEGF expression and enhances angiogenesis in human chondrosarcoma cells through a signal transduction including TrkB receptor, PLCγ, and PKCα." (PMID 26811493, 2016). "In this study, we explored the involvement of the intracellular ASK1 signaling pathway in BDNF-induced MMP-1 production and cell migration in human chondrosarcoma." (PMID 23892595, 2013). "However, the effect of BDNF on migration activity in human chondrosarcoma cells is mostly unknown." (PMID 23874483, 2013). "Based on these results, BDNF appears to act via the TrkB receptor and the ASK1 and JNK/p38-dependent signaling pathways to enhance cell migration and MMP-1 production in human chondrosarcoma cells." (PMID 23892595, 2013).
chondrosarcoma (continued). "Pretreatment of chondrosarcomas with PI3K inhibitors (Ly294002 and wortmannin) abolished BDNF-mediated cell migration and β5 integrin expression." (PMID 23874483, 2013). "From these results, it appears that the BDNF/TrkB axis acts through the PI3K/Akt-dependent signaling pathway to enhance β5 integrin expression and cell migration in human chondrosarcoma cells." (PMID 23874483, 2013). "The results showed that BDNF-induced migration and invasion ability, as well as MMP-1 up-regulation of chondrosarcoma cells, were greatly reduced by pretreatment with the ASK1 inhibitor thioredoxin." (PMID 23892595, 2013). "Pretreatment of chondrosarcoma cells with PI3K, Akt, and NF-κB inhibitors or mutants also abolished BDNF-promoted migration and integrin expression." (PMID 23874483, 2013). "However, the effect of BDNF on cell motility in human chondrosarcoma cells is mostly unknown." (PMID 23892595, 2013). "However, the effect of BDNF in human chondrosarcoma migration remains largely unknown." (PMID 23892595, 2013). "We also found that BDNF increased cell motility and expression of matrix metalloproteinase-1 (MMP-1) in human chondrosarcoma cells." (PMID 23892595, 2013). "In addition, we demonstrate a clinical correlation between BDNF and VEGF-C in human chondrosarcoma tissue." (PMID 28771226, 2017). "Thus, our results show that BDNF promotes VEGF-C expression and lymphangiogenesis in human chondrosarcoma cells via the MEK/ERK/mTOR signaling pathway." (PMID 28771226, 2017). "First, the expression of BDNF was significantly higher in chondrosarcoma cells than in normal chondrocytes, and correlated strongly with cell motility." (PMID 23892595, 2013). "The current study demonstrated that BDNF increases MMP-1 expression by binding to the TrkB receptor and activating the ASK1, JNK/p38, and Sp1-dependent pathways, thereby enhancing the migration and invasion activity of human chondrosarcoma cells." (PMID 23892595, 2013). "The results showed that BDNF binds to TrkB, which activates the ASK1, JNK/p38, and Sp1 pathways, leading to up-regulated MMP-1 expression, resulting in the promotion of migration of human chondrosarcoma cells." (PMID 23892595, 2013). "Therefore, activation of the TrkB receptor and the ASK1, JNK/p38, and Sp1 pathways are required for BDNF-induced cell migration and MMP-1 production in human chondrosarcoma cells." (PMID 23892595, 2013). "Therefore, our results provide evidence that BDNF up-regulates MMP-1 expression and cell migration in human chondrosarcoma cells via the ASK1 and JNK/p38 signaling pathways." (PMID 23892595, 2013). "Moreover, transfection of cells with ASK1 shRNA inhibited BDNF-induced motility and MMP-1 expression in chondrosarcoma cells." (PMID 23892595, 2013).
Dyskinesia (16 papers, 2014 to 2024). A movement disorder which consists of effects including diminished voluntary movements and the presence of involuntary movements. "We found ANNK1 and BDNF variants to be nominally significantly associated (P < 0.05) with the time to dyskinesia." (PMID 37425912, 2023). "In another study, the carriers of dopamine receptor DRD2 and DRD3 haplotypes, as well as the BDNF variant rs6265, were associated with an increased risk of dyskinesia, suggesting that these genes may be implicated in dyskinesia-related pathomechanisms in Parkinson’s disease patients." (PMID 35743271, 2022). "It was reported in recent years that several genetic variations (such as COMT Val158Met, BDNF val66met, mu opioid receptor polymorphism and dopamine D2 receptor intronic dinucleotide repeat polymorphism) were associated with the occurrence of motor complications, especially for dyskinesia." (PMID 25671102, 2014). "On the other hand, SNPs in the mTOR pathway genes, BDNF, HOMER1 and DAT have been implicated in either increased or reduced risk for dyskinesias, but with single studies that are yet to be corroborated in larger cohorts." (PMID 34281267, 2021). "BDNF levels in the lesioned striatum had a positive linear correlation with total dyskinesia scores at the time of the last dyskinesia measurement (n = 12, r = 0.582, P = 0.047)." (PMID 30497382, 2018). "Other polymorphisms including rs886292 (ABCC8), rs11880894 (RYR1), rs1800497 (DRD2), rs6265 (BDNF), rs11646587, rs7192557 and rs8057394 (GRIN2A) were found to be associated with dyskinesia in patients administered with levodopa medication." (PMID 28927418, 2017). "Moreover, BDNF-TrkB signaling in striatal D1-MSNs has a protective effect against the development of levodopa-induced dyskinesias (LID), with targeted activation of TrkB agonists reducing LID severity." (PMID 38802497, 2024). "Conversely, the administration of L‐dopa in the MPTP monkey model was associated with a reduction of BDNF expression independent of dyskinesia." (PMID 38752280, 2024). "Carriers of dopamine receptors DRD2 haplotypes and possibly the BDNF variants rs6265 and DRD3 haplotypes, were at increased risk of dyskinesia, suggesting that these genes may be involved in dyskinesia-related pathomechanisms." (PMID 35743271, 2022). "Another study performing cerebellar theta burst stimulation showed a reduction of levodopa-induced dyskinesias together with a decrease in serum BDNF levels, which further provides indirect evidence that an increase in BDNF levels could be associated with dystonic symptoms." (PMID 39200225, 2024). "L‐dopa‐induced dyskinesia may be due to the overexpression of BDNF." (PMID 38752280, 2024). "Indeed, levodopa treatment was shown to increase the corticostriatal BDNF expression that helps to restore the compromised neuronal plasticity in the stratum in PD, which in turn improved motor skills, but may also contribute to the development of dyskinesias." (PMID 37511603, 2023). "Brain-derived neurotrophic factor (BDNF) is involved in the pathophysiology of PD and L-DOPA-induced dyskinesias." (PMID 37936189, 2023). "No other statistically significant correlations between dyskinesia scores and BDNF levels were found." (PMID 30497382, 2018). "For analysis of correlation between striatal BDNF and dyskinesia severity, control and nicotine groups were combined as neither dyskinesia severity at the end of the experiment nor striatal BDNF levels differed between groups." (PMID 30497382, 2018).
experimental autoimmune encephalomyelitis (16 papers, 2008 to 2025). An autoimmune demyelinating disease of the central nervous system that is produced experimentally in animals by the injection of homogenized brain or spinal cord in Freund's adjuvant. "A pathogenic link between alterations of circulatory BDNF and autoimmune inflammation was assumed for experimental autoimmune encephalomyelitis, systemic lupus erythematosus, sclerosis, inflammatory bowel disease etc.." (PMID 36498925, 2022). "In a mouse model of experimental autoimmune encephalomyelitis, depletion of astrocyte-specific BDNF increases disease severity." (PMID 37019946, 2023). "It has been previously reported that different growth factors (i.e., BDNF) exert anti-inflammatory and anti-apoptotic effects in a murine model of MS (i.e., experimental autoimmune encephalomyelitis, EAE)." (PMID 29655371, 2018). "We hypothesized that BDNF in immune cells might be a prerequisite to reduce disease activity in experimental autoimmune encephalomyelitis (EAE) and prevent neurotoxicity." (PMID 39090252, 2024). "We hypothesize that following experimental autoimmune encephalomyelitis (EAE)-induced myelin damage, the immune system induction of the pathogenic MeCP2E1 isoform hampers the myelin repair process by repressing BDNF expression." (PMID 28604632, 2017). "In a rat model of experimental autoimmune encephalomyelitis, the administration of matrine suppressed the reduction of nerve fibers in the brain, which might relate to the increased level of brain-derived neurotrophic factor mRNA." (PMID 26834638, 2015).
iron deficiency (16 papers, 2011 to 2025). "Early-life iron deficiency in rats was shown to alter DNA and histone methylation at the gene encoding brain-derived neurotrophic factor (BDNF), important for neural function in the hippocampus." (PMID 38760200, 2024). "The level of sEV BDNF was inversely correlated with cord ferritin levels and maternal iron deficiency." (PMID 38435713, 2023). "The difference in the relationship of sEV BDNF versus plasma levels with iron deficiency, and changes in the forms (pro- or mature form) in the sEVs with psychiatric conditions, support pro-BDNF/BDNF being cargo in sEV." (PMID 38435713, 2023). "In contrast, plasma BDNF was reported to be lowered in the umbilical cord blood of neonates from mothers with iron deficiency." (PMID 38435713, 2023). "Both human and animal studies have shown that maternal iron deficiency affects the fetal production of BDNF and hippocampal morphogenesis." (PMID 32825437, 2020). "Our findings suggest that fetal and perinatal iron homeostasis is important for the expression of BDNF in brain development, and provides a molecular basis for the spatial learning deficits related to maternal iron deficiency." (PMID 32825437, 2020). "Early-life iron deficiency followed by dietary iron repletion resulted in altered hippocampal BDNF and tyrosine receptor kinase B (TRKB) expression in pigs at 12 weeks of age, thus indicating lasting effects of an early-life ID diet on hippocampal development." (PMID 29375469, 2017). "Young rats whose mothers were fed an iron-deficient diet and who were born with iron deficiency, showed decreased brain-derived neurotrophic factor (BDNF) levels, down-regulation of BDNF target genes, and altered neuronal differentiation." (PMID 24065908, 2013). "Iron deficiency in the pre- or postnatal period reduced BDNF and neurogenesis in the hippocampal dentate gyrus of pups." (PMID 24065908, 2013). "Fetal-neonatal iron deficiency persistently suppresses BDNF expression in the adult rat hippocampus, suggesting a possible role for epigenetic modifications." (PMID 24303168, 2013). "Iron deficiency leads to decreased expression of SERT which in turn exacerbates the decreased expression of BDNF." (PMID 24065908, 2013). "This may affect the mTOR (Mammalian Target of Rapamycin) pathway and BDNF (brain-derived neurotrophic factor) expression, potentially causing long-term brain dysfunction that persists even after iron deficiency is corrected after birth." (PMID 40429475, 2025). "Furthermore, maternal iron deficiency in a mouse model can lead to offspring exhibiting decreased BDNF expression in the brain, spatial learning deficits and an altered faecal microbiota profile." (PMID 37445611, 2023). "Umbilical cord sEV BDNF can serve as a potential marker for iron deficiency and neonatal brain status, and may have a role in neuroprotection." (PMID 38435713, 2023). "In this study, we showed that maternal iron deficiency may program and alter adult male offspring development with regard to spatial learning and memory, dorsal hippocampus BDNF expression, gut microbiota, and SCFA concentrations." (PMID 32825437, 2020). "We next examined whether an iron deficiency altered the mRNA and protein concentrations of the BDNF signaling pathway within the dorsal hippocampus." (PMID 32825437, 2020). "Both serum BDNF concentrations and hippocampal volumes of human neonates born to iron-deficient mothers are significantly low, and the magnitude of reduction is proportional to the severity and duration of the maternal iron deficiency." (PMID 32825437, 2020). "Our results imply that maternal iron deficiency may program adult male offspring, reducing the dorsal hippocampal BDNF concentration and altering the TrkB cascade, which is required for spatial learning and memory." (PMID 32825437, 2020).
iron deficiency (continued). "Two studies focusing on iron deficiency have shown that deficits in recognition memory could be mitigated by prenatal choline supplementation, possibly by preserving hippocampal brain-derived neurotrophic factor and myelin basic protein expression." (PMID 32531929, 2020). "To provide a potential link between fetal-neonatal iron status and iron-dependent chromatin modifiers and to gain insight into a possible mechanism underlying BDNF gene regulation during iron deficiency, we analyzed expression of histone H3 demethylases (JARIDs) that require iron as a cofactor." (PMID 24303168, 2013). "Notably, expression of brain-derived neurotrophic factor (BDNF), a gene critical for neuronal maturation and synaptic plasticity, is lowered both acutely and in adulthood following early-life iron deficiency." (PMID 24303168, 2013). "On the basis of the existing literature, we hypothesized that early-life iron deficiency persistently alters hippocampal BDNF expression in the F2 offspring of FID rats." (PMID 24303168, 2013). "The small upregulation of Hif1a during iron deficiency anemia (P15 ID) was likely driven by cellular hypoxia, whereas its upregulation in the F2 IS could be driven by BDNF/TrkB signaling." (PMID 24303168, 2013). "This study addressed whether early iron deficiency alters BDNF expression across generations." (PMID 24303168, 2013). "The expression of BDNF by neurons is sensitive to iron levels as demonstrated by studies showing that dietary iron deficiency reduce BDNF expression without affecting expression of the BDNF receptor TrkB." (PMID 21949858, 2011). "Collectively, the findings reveal that early iron deficiency does not result in a lasting dysregulation of BDNF across multiple generations and suggest that early iron deficiency does not lead to heritable epigenetic modifications of BDNF regulation and function." (PMID 24303168, 2013). "Given the known role of vitamin D and magnesium deficiency in the pathogenesis of many non-communicable disorders, we will test the effects of their co-supplementation in obese women on the readouts of mood and serum levels of BDNF, inflammatory cytokines, and SIRT1." (PMID 32102680, 2020). "Given that early iron deficiency occurs during critical periods in both hippocampal and gonadal development, we hypothesized that the iron-sufficient offspring (F2 IS) of formerly iron-deficient (F1 FID) rats would show a similar suppression of the BDNF gene as their parents." (PMID 24303168, 2013). "Thus, the lack of difference in BDNF in the prefrontal cortex of 12-week-old pigs and our observation of similar brain volumes at 8 weeks of age between ID and CONT pigs may suggest neuron outgrowth was not drastically influenced by early-life iron deficiency." (PMID 29382055, 2018).